SNORD53B (small nucleolar RNA, C/D box 53B)
Gene: Small nucleolar RNA gene on chromosome 2 (28,927,983 to 28,928,060, forward strand). Ensembl gene ENSG00000265706.
Gene Ontology:
Biological process: RNA processing
Cellular component: nucleolus
Homologues: Orthologues: chimpanzee SNORD53B (100% identical), macaque SNORD53B (95% identical), guinea pig SNORD53B (94% identical), rat Snord53b (92% identical), mouse Gm22858 (91% identical), pig SNORD53B (91% identical), rabbit SNORD53B (86% identical). Paralogues in human: SNORD53 (78% identical), SNORD92 (64% identical).